PVT1 (Pvt1 oncogene)
Diseases named in the same sentence as PVT1 in open-access papers (continued):
Sharing a sentence is not in itself a finding about the gene and the disease.
gallbladder cancer (21 papers, 2019 to 2024). "lncRNA plasmacytoma variant translocation 1 (PVT1) has been reported as a tumor promoter in multiple malignancies such as gallbladder cancer and esophageal adenocarcinoma." (PMID 36760720, 2023). "In parallel, as a marker associated with gallbladder cancer, lncRNA PVT1 has been reported to induce invasion, metastasis and apoptosis resistance of gallbladder cancer cells by silencing HK2 via upregulation of miR-14326." (PMID 37859812, 2023). "Sun and colleagues reported that lncRNA plasmacytoma variant translocation 1 (PVT1) acts as an oncogenic lncRNA in gallbladder cancer (GBC) by sponging and repressing miR-143, allowing HK2 to be overexpressed." (PMID 33652661, 2021). "Gallbladder cancer tissues and cells upregulate PVT1 and downregulate miR-30d-5p, thus promoting proliferation by sponging miR-30d-5p expression, which is reversed by PVT1 knockdown." (PMID 37190145, 2023). "For example, lncRNA PVT1 promotes tumor progression by regulating the miR-143/HK2 axis in gallbladder cancer." (PMID 35477447, 2022). "In gallbladder cancer, the lncRNA PVT1 which was positively related to malignancies and worse overall survival time was upregulated in gallbladder cells." (PMID 34196116, 2021). "In gallbladder carcinoma, PVT1 competitively binds to miR‐143, reduces miR‐143's inhibitory effect on HK2 and promotes cell proliferation and migration." (PMID 32368853, 2020). "PVT1 regulates the expression of HK2 in gallbladder cancer cells by competitive binding to miR-143, and controls aerobic glucose metabolism to promote cell proliferation and metastasis." (PMID 32153626, 2019). "Abnormal expression of PVT1 has been reported in gallbladder cancer." (PMID 38184562, 2024). "Recent studies have shown that PVT1 modulates the expression of HK2 by competing with endogenous miR-143 in gallbladder cancer (GBC) cells, which could provide valuable insights into the potential therapeutic targets for GBC at the molecular level." (PMID 38383348, 2024). "Therefore, curcumin and cardamonin can potentially suppress the proliferation of gallbladder cancer cells by modulating the PVT1–miR-30d-5p axis." (PMID 37190145, 2023). "LncRNA PVT1 has been reported to play important roles in various cancers, but its role in gallbladder cancer remains unknown." (PMID 33067424, 2020). "It is reported that the expression of lncRNA PVT1 is up-regulated in tumors, which regulates HK2 expression by competitively binding to endogenous miR-143 in gallbladder cancer cells and promotes aerobic glycolysis of tumor cells." (PMID 36292959, 2022). "Long noncoding RNA PVT1 inhibits miR-18b-5p expression by recruiting DNMT1, and DNMT1 promotes miR-18b-5p methylation, thereby promoting gallbladder cancer proliferation." (PMID 34362460, 2021). "Moreover, the PVT1/miR-143/HK2 axis promotes cell growth and metastasis by modulating aerobic glucose metabolism in gallbladder cancer cells." (PMID 38184562, 2024). "PVT1 and HK2 act as a ceRNA of miR‐143, which could regulate aerobic glucose metabolism in gallbladder cancer cells, and promote cell proliferation and metastasis." (PMID 34196116, 2021).
liver cancer (20 papers, 2015 to 2025). An epithelial or non-epithelial malignant neoplasm that arises from the liver. "MiR-214-3p, in turn, competitively binds to GPX4, inducing iron-mediated apoptosis via PVT1/miR-214-3p/GPX4 axis in liver cancer (He GN." (PMID 40176927, 2024). "The lncRNA plasmacytoma variant translocation 1 (PVT1) has been found to be elevated in nearly all GI tumors including gastric, esophageal, pancreatic, colon, and liver cancers." (PMID 29967761, 2018). "Pvt1 is the linear transcript of circ_011235 and was found to promote proliferation and stem cell property of liver cancer." (PMID 27677588, 2016). "A meta-analysis has shown that PVT1 has moderate value in discriminating HCC from control with a summary receiver operating characteristic of 0.81 (95%CI: 0.77–0.84), thus suggesting the potential of PVT1 as a diagnostic indicator for liver cancer." (PMID 31497532, 2019). "Furthermore, the expression of PVT1 was defined in 10 liver cancer cell lines and one healthy liver cell line." (PMID 25624916, 2015). "It has been shown that the overexpression of LncRNA plasmacytoma variant translocation 1 (PVT1), which is associated with multiple cancer types, can modulate the expression levels of GPX4 by suppressing miR-214-3p, hence promoting ferroptosis inhibition in liver cancer." (PMID 38738178, 2024). "In conclusion, the present study demonstrated that PVT1 was overexpressed in two independent human HCC cohorts and 10 liver cancer cell lines." (PMID 25624916, 2015). "Of the 10 liver cancer cell lines, six (HepG2, SK-Hep1, MHCC-97L, SMMC-7721, MHCC-97H and Bel-7402) expressed a higher level of PVT1 than the healthy liver cell line." (PMID 25624916, 2015).
pancreatic ductal adenocarcinoma (20 papers, 2016 to 2025). An infiltrating adenocarcinoma that arises from the epithelial cells of the pancreas. "PVT1 expression levels were positively associated with that of ULK1 in pancreatic ductal adenocarcinoma tissues." (PMID 33050642, 2020). "Similarly, lncRNA PVT1 was overexpressed in human pancreatic ductal adenocarcinomas (PDAC) and was associated with reduced patient survival." (PMID 40861273, 2025). "Curcumin plays an essential role in inducing hypersensitivity to chemotherapy in the gemcitabine-resistant pancreatic ductal adenocarcinoma (PDAC) cell by inhibiting the PRC2/PVT1/c-Myc axis." (PMID 33805687, 2021). "Recent studies reported lncRNA PVT1 was highly expressed in pancreatic ductal adenocarcinoma (PDAC) tissues, and correlated with clinical stage." (PMID 29108264, 2017). "Thus, it was concluded that upregulation of PVT1 promotes the progression of pancreatic ductal adenocarcinoma and glycolysis by regulating miR-519d-3p and HIF-1A." (PMID 40861273, 2025). "Pancreatic ductal adenocarcinoma (PDAC)-produced IL-6 induced the expression of the lncRNA plasmacytoma variant translocation 1 (PVT1) in tumor-associated nonmyelinating Schwann cells (TASc)." (PMID 37767098, 2023). "LncRNA PVT1 could promote the development of pancreatic ductal adenocarcinoma by serving as a sponge to miR-20-5p." (PMID 34294156, 2021). "In addition, high expression of HIF-1α, which is regulated by the LncRNA PVT1/miR-519d-3p axis, promotes glycolysis and pancreatic ductal adenocarcinoma progression." (PMID 33154192, 2020). "Curcumin reduced the expression of PVT1 lncRNA by inhibiting EZH2 and SUZ12 in pancreatic ductal adenocarcinoma cells." (PMID 33805687, 2021). "Further study showed that PVT1 functioned as an miRNA sponge of miR-20a-5p and restored the expression of ULK1 in the progression of pancreatic ductal adenocarcinoma." (PMID 33050642, 2020).
lymphoma (17 papers, 2008 to 2023). A malignant (clonal) proliferation of B- lymphocytes or T- lymphocytes which involves the lymph nodes, bone marrow and/or extranodal sites. "Plasmacytoma variant translocation 1 (PVT1) lncRNA was firstly discovered in murine leukemia virus-induced T lymphomas as a ubiquitous retroviral integration site; PVT1 acts as oncogenic lncRNA in many cancers." (PMID 36229883, 2022). "PVT1 is plasmocytoma variant translocation 1 gene (PVT1), an oncogene described as a site of retroviral insertions in murine T lymphomas." (PMID 29033906, 2017). "Moreover, it harbors a number of susceptibility loci at 8q24.21 near or in the PVT1 gene, such as single nucleotide variants in different types of lymphoma." (PMID 32228602, 2020). "An analysis of the co-mutations in the lymphomas likely place Pvt1 and Myc into the same pathway." (PMID 18194563, 2008). "Originally, lncRNA PVT1 was recognized as a normal retroviral integration site in murine leukemia virus-induced T lymphomas." (PMID 35038974, 2022). "Despite the frequency of genomic alterations and rearrangements, few studies investigated the functional role of PVT1 in lymphomas." (PMID 32228602, 2020). "Among the microRNAs regulated by PVT1, miR-26b, miR-203a, miR-214, miR-424 and miR-497 were reported to be deregulated and play a role in the pathogenesis of lymphoma and/or MM and/or leukemia." (PMID 32228602, 2020). "PVT1 was originally identified as a common retroviral integration site in murine leukaemia virus (MLV)-induced T lymphoma." (PMID 29137343, 2017). "The Pvt1 locus (known PVT1 as in humans) is a common retroviral integration site in induced T lymphomas in rodents." (PMID 19440463, 2008). "Pvt1 is also a common retroviral integration site in murine leukemia virus (MLV) induced T lymphomas in mice and rats." (PMID 18194563, 2008). "This evidence suggests that PVT1 acts as an oncogene to promote lymphoma growth." (PMID 36195846, 2022). "Genomic events targeting the PVT1 locus have been also described in other lymphoma types." (PMID 32228602, 2020). "The Pvt1 locus is among the top targets of retroviral insertions in T lymphomas, but it encodes transcripts with no known protein product." (PMID 18194563, 2008). "Although the pathogenic role of PVT1 in lymphoma is not precisely known, the examination of whether the microRNAs and/or circPVT1 transcribed from the PVT1 locus are linked to tumorigenesis and drug sensitivity in AMU‐ML2 cells is worthy of further study." (PMID 30524948, 2018). "Indeed, NGS data showed that this particular lymphoma harbored an Igh-Pvt1 translocation." (PMID 26740101, 2016). "Translocations affecting the 8q24 locus are well-documented in multiple myeloma, lymphoma and chronic lymphocytic leukaemia, and generally result in MYC (located 53 Kb upstream of PVT1) and PVT1 overexpression; these events are associated with poor prognosis." (PMID 34754096, 2022).
medulloblastoma (17 papers, 2013 to 2025). A malignant, invasive embryonal neoplasm arising from the cerebellum. "The generation of fusion products NDUFAF2::MAST4 in prostate cancer and PVT1::NDRG1 in medulloblastomas are both associated with chromothripsis but remain poorly-defined in terms of contribution to malignancy." (PMID 40359993, 2025). "To assess that, we probed the prevalence of PVT1 fusion events across distinct Medulloblastoma (MB) subgroups." (PMID 40027648, 2025). "Beyond supratentorial ependymomas, chromothripsis derived oncogenic fusion products have been documented with regards to PVT1::MYC in medulloblastoma, RLF::MYCL1 in small cell lung cancer and HNRNPM::LEUTX in small round cell neoplasms." (PMID 40359993, 2025). "A study investigated copy number variations in medulloblastoma identified translocation of PVT1 as a novel molecular subtype." (PMID 38287522, 2024). "The outlier with the highest number of fusion reads in medulloblastoma is sample 67 from the Group 3 subtype, with most of these reads originating from the PVT1--CASC8 linear fusion." (PMID 35804907, 2022). "Chromothripsis in medulloblastoma leads to recurrent translocations that eventually fuse a lncRNA PVT1 to MYC, resulting in a continuous oncogenic effect via MYC amplification." (PMID 33557176, 2021). "The PVT1–MYC fusion is the most frequently detected fusion that is identified in 60% of MYC-amplified group 3 medulloblastomas (12 out of 20 samples)." (PMID 34830991, 2021). "The tumorigenic role of c-MYC in medulloblastoma is further complicated by RNA-Seq studies showing persistent gene fusions involving the 5′ end of PVT1, a noncoding gene, which frequently coamplifies with c-MYC." (PMID 27775567, 2016). "A fascinating fact that we highlight in this review is that the lncRNA PVT1 is part of several gene fusions with mRNAs in numerous types of cancer, from leukemias to solid tumors such as breast, lung, prostate, esophagus, medulloblastoma, ovarian, stomach and uterine cancer." (PMID 38292185, 2024). "Moreover, in another medulloblastoma sample (sample 74), the same PVT1 exon is spliced to a number of exons about 35Mb away from the PVT1 locus." (PMID 35804907, 2022). "Importantly, PVT1, a non-coding oncogene, neighbors the MYC oncogene, with both genes known to be amplified in cancer, and the medulloblastoma samples harboring the observed PVT1 fusions belong to the Group 3 medulloblastoma subtype, characterized by MYC amplifications." (PMID 35804907, 2022). "The oncogenic effect of mutations in the fusion genes such as ARID1A, PVT1, GFI1, MYCN, DNMT1, and TET3 has been identified in various tumors including medulloblastomas to regulate tumorigenesis, suggesting that the predicted inframe fusion proteins may possess oncogenic potential." (PMID 33681213, 2021). "One example of this is in medulloblastoma, where MYC was shown to increase its own expression by binding PVT1 in a positive feedback loop." (PMID 37958407, 2023). "Additional selected linear fusions in medulloblastoma that cannot be interpreted via read-through transcription are the TFG--ADGRG7 and the PVT1--CASC8." (PMID 35804907, 2022). "In the Medulloblastoma Advanced Genomics International Consortium (MAGIC) study, RNA-seq of medulloblastoma Group 3 tumors identified two different PVT1 gene fusions." (PMID 32117705, 2020). "Examples of this characteristic event are PVT1-MYC and PVT1-NDRG1 fusions in medulloblastoma, and NDUFAF2-MAST4 in prostate cancer cell lines." (PMID 31007851, 2019). "Additionally, RT-PCR demonstrated the upregulation of miR-1204 in PVT1-MYC fusion (+) Group 3 tumors and an increase in cell proliferation of specific medulloblastoma cells; proposing a regulatory system among fusion partners in oncogenesis." (PMID 32117705, 2020). "These are particularly important when dealing with genomic aberrations that occur in non-gene-coding regions, such as seen with PVT1–MYC gene fusions in Group 3 medulloblastomas." (PMID 27775567, 2016).
renal carcinoma (15 papers, 2016 to 2023). A carcinoma arising from the epithelium of the renal parenchyma or the renal pelvis. "HIF binding, activity and accessibility of the enhancer as well as MYC/PVT1 induction are restricted to cells from renal tubular origin and dependent on the genotype of rs35252396, a polymorphism associated with renal cancer susceptibility." (PMID 27774982, 2016). "It has been reported that ccRCC has the strongest upregulated expression of PVT1 among all cancer types and served as a prognostic factor of renal cancer." (PMID 36438902, 2022). "Among all the lncRNA candidates predicted by the BiGAN as being associated with renal cancer, 7 lncRNAs were among the top 10 in the predicted list, (MALAT1 1st, HOTAIR 2nd, PVT1 3rd, NBAT1 4th, UCA1 5th, H19 6th, and MEG3 7th)." (PMID 34193046, 2021). "Here we revealed that PVT1 protected HIF2α from polyubiquitination and subsequent proteasomal degradation in VHL-deficient renal cancer cells." (PMID 34321604, 2021). "The PVT1 lncRNA has been found overexpressed in ccRCC tissue explants, as well as in renal cancer cell lines A498, 786-O, ACHN, and Caki-1." (PMID 33920158, 2021). "Western blot of cleaved PARP and cleaved Caspase-3 revealed that Mcl-1 promotes PVT1-induced renal cancer cell growth and inhibits apoptosis in vivo." (PMID 29254209, 2017). "In this study, we proved that PVT1 is upregulated in both renal cancer tissues and cell lines, and it is correlated with a variety of clinicopathological factors including TNM staging and distant metastasis." (PMID 29156724, 2017). "In vitro experiments revealed that PVT1 promoted renal cancer cell proliferation, migration, and invasion, while in vivo studies confirmed its oncogenic roles in ccRCC." (PMID 29156724, 2017). "PVT1 knockdown promoted apoptosis, inhibited renal cancer cell proliferation, decreased Mcl-1, and increased cleaved caspase-3 and cleaved PARP." (PMID 29254209, 2017). "Rather than enhancing transcriptional activity of the Mcl-1 promoter, our data showed that PVT1 enhanced the stability of Mcl-1 mRNA in renal cancer cells." (PMID 29254209, 2017). "Collectively, our study discloses the role of PVT1 as a novel prognostic factor and as a molecular target for novel therapeutic interventions in renal carcinoma." (PMID 27366943, 2016). "As a first step in analysing mechanisms associated with variant rs35252396, we therefore sought to define the frequency of dysregulated MYC and PVT1 expression in renal cancer." (PMID 27774982, 2016). "That many of the currently known renal cancer-associated SNPs (EPAS1, CCND1 and MYC/PVT1) can be linked to modulation of a single pathway (that is, the HIF pathway) is striking and to our knowledge unique in tumour biology." (PMID 27774982, 2016). "Strikingly, significant induction of both MYC and PVT1 RNA by DMOG was specifically observed in renal cancer cell lines and tubular cells." (PMID 27774982, 2016). "We also showed that PVT1 inhibits renal cancer cell apoptosis by enhancing Mcl-1 mRNA stability." (PMID 29254209, 2017). "We also identified the oncogenic function of PVT1 in renal cancer cells." (PMID 29156724, 2017). "Moreover, our study revealed that PVT1 knockdown could inhibit proliferation and induce apoptosis of renal cancer cells in vivo and in vitro." (PMID 29254209, 2017). "We also examined the expression of PVT1 in renal cancer cell lines and immortalized human proximal renal tubule epithelial cell line HK-2 by real-time PCR analysis, which demonstrated that PVT1 expression was consistently upregulated in a panel of 4 human renal cancer cell lines compared to HK-2." (PMID 29156724, 2017). "Thus, our data suggest that PVT1 may act as an oncogene in renal carcinoma via stabilization of MYC protein, and subsequently activation of MYC pathway." (PMID 27366943, 2016).
renal carcinoma (continued). "We demonstrate here that unrestrained activation of HIF in pVHL-defective renal cancer enhances expression of MYC and PVT1 via long distance interactions with a HIF-binding intergenic enhancer." (PMID 27774982, 2016). "PVT1 increased Mcl-1 mRNA levels in renal cancer cells by promoting mRNA stability without influencing its transcription." (PMID 29254209, 2017). "To explore the role of PVT1 in renal cancer cells, we stably regulated the expression of PVT1 in two RCC cell lines 786-O and ACHN with lenti-viral system, using short hairpin RNA (shRNA) or full-length PVT1 plasmid to silence or overexpress the PVT1 respectively." (PMID 29156724, 2017). "This revealed robust HIF-binding signals across a series of pVHL-defective renal cancer cell lines as well as immortalized proximal tubular and primary tubular cells in which HIF was stabilized by hypoxia or DMOG at intergenic sites located between the MYC and PVT1 genes." (PMID 27774982, 2016). "We also found a positive correlation between PVT1 and BMI1, ZEB1 and ZEB2 as well as a negative correlation between miR-200c and PVT1, BMI1, ZEB1 and ZEB2 in our 50 paired renal cancer tissues through RT-PCR, which was consistent with that of the analysis from TCGA Data Portal." (PMID 29156724, 2017).